IL10 (interleukin 10)
Diseases named in the same sentence as IL10 in open-access papers (continued):
Sharing a sentence is not in itself a finding about the gene and the disease.
infection (continued). "Notably, the “IL-10 signaling” pathway ranked 149th at 6 hpi in that study, whereas, in ours, we observed a more consistent and continuous progression of the infection in terms of the number and composition of DE genes and their associated pathways." (PMID 31969876, 2019). "The levels of cytokines in the supernatants of these cultures revealed a significant increase in TNF-α, IFN-γ, IL-10, and GM-CSF only in the control group after 24 h of L. amazonensis infection, with a gradual increase until 72 h post-infection, as compared to the IGHD subjects (p < 0.05)." (PMID 31544067, 2019). "Furthermore, although IL10 was differentially expressed by bMDM in response to infection with the two M. bovis strains, the cytokine promoted the early survival of both strains." (PMID 31527895, 2019). "However, the addition of exogenous IFNG significantly inhibited the production of IL10 protein in response to infection with both M. bovis strains." (PMID 31527895, 2019). "Infection of both resting and IL-4 activated macrophages induced the production of IL-10, thus raising the possibility that this cytokine acts in an autocrine manner to maintain the alternative activation phenotype, or induces it in the case of resting macrophages." (PMID 31134002, 2019). "We also noted that STAT3 might play a central role in the interplay of IL-17 and IL-10 during infection and it may be a new target for the therapy of PCP in the future." (PMID 31582901, 2019). "Nevertheless, since several cell types are capable of producing IL-10 during infections, it remains unclear whether NK cell-derived IL-10 plays a definitive role in the regulation of inflammatory processes during sustained MCMV infection." (PMID 31803193, 2019). "Although it cannot rule out that other regulatory cytokines could also be involved, our results demonstrate the regulatory participation of IL-10 in the early stages of the infection." (PMID 30881362, 2019). "Next, we investigated whether NK cell-specific IL-10 ablation in perforin-deficient mice leads to a reduction in the systemic levels of IL-10 during infection." (PMID 31803193, 2019). "We propose that the secretion of IL-10 in the intestine might be delayed, and measurable later than 24 hrs post-infection." (PMID 31540295, 2019). "The anti-inflammatory cytokine, IL-10 arises as a major immune-regulator at the occurrence of infection with bacteria, fungi, protozoa and viruses and helminths, improve the excessive response of Th1 and CD8+ T cells represented by over synthesis of IFN-γ and TNF-α58." (PMID 31289291, 2019). "Later in infection, the expression of genes encoding for pro-inflammatory cytokines is down-regulated in spleens and lungs, while the expression of regulatory factors increases in lungs (e.g., Foxp3, TGF-b, IL10 in rats,)." (PMID 31331096, 2019). "Furthermore, we examined the kinetics of IL-10 mRNA in PAMs response to the infection of PCV1, PCV2, and recombinant viruses (PCV1-Rep2, PCV2-Rep1)." (PMID 31835539, 2019). "Interleukin-10 is involved in down-regulating macrophage and helper T-cell function and is a key immunoregulator during infection that may mitigate tissue damage from excessive cytotoxicity." (PMID 31316998, 2019). "Differences in the outcome of IL-10 deficiency could, in part, be explained by different virus strains or doses of infection and the time of IL-10 blockade." (PMID 30998505, 2019). "We speculate that IL-10-producing MHC II+ neutrophils are induced in abomasal DLNs in the days following an OO priming infection, then quickly decline to undetectable levels in cattle with extended and repeated OO exposure." (PMID 31889109, 2019). "Although IL-10 was elevated in mice administered alcohol compared to control mice not administered alcohol, no statistical difference in IL-10 was measured among the groups of mice administered alcohol at any time prior to infection." (PMID 31821337, 2019).
infection (continued). "The IL-10 production is said to be elevated during the infection, promoting reactivation of TB." (PMID 30583589, 2018). "This suggests that the production of IL-1β and reduction in IL-10 mediated by properdin may be required for protection against M. tuberculosis in the initial phase of infection." (PMID 29867915, 2018). "Hence these observations indicate that the intense IL-10 production observed upon infection with KR WT or KR cps- is specific of K. rhinoscleromatis and does not result from a global high bacterial load." (PMID 29381692, 2018). "Therefore, we cannot definitely exclude that IL-10 dampens the control of mycobacterial growth and contributes to the increased bacterial loads at a later time point of infection." (PMID 29675017, 2018). "Secondly, both IL-10 and IFNγ were more elevated during severe C0360/94 infection at 800 pg/ml and 1,200 pg/ml, respectively, compared to the 60 pg/ml and 250 pg/ml, respectively, during D83-144 infection." (PMID 29559699, 2018). "Moreover, we found restored levels of IL-10 in the lymph nodes 4 days after infection in RvD2-treated mice." (PMID 29922275, 2018). "This cytokine was protective during systemic infection, dampening potential pathological activation while conversely, during a local subcutaneous infection, IL-10 was found to support bacterial growth indicating that IL-10 production could benefit S. aureus." (PMID 29843476, 2018). "Since the MDR-bacteria and non-MDR bacteria present different virulence, it is possible to hypothesize that MDR-bacteria induce differential amounts of IL-10 during infection." (PMID 30279680, 2018). "During a MRSA (USA300) infection there is a rapid production of IL-10." (PMID 30279680, 2018). "In infection models, there are also two distinct subpopulations of neutrophils: pro-inflammatory neutrophils (N1: IL-12 and macrophage inflammatory proteins producing) and anti-inflammatory neutrophils (N2: IL-10 and CCL2 producing)." (PMID 29776443, 2018). "Moreover, the rhesus CMV IL-10 orthologue restricts inflammation at the site of infection whilst suppressing long-lived virus-specific immunity in vivo." (PMID 29768502, 2018). "Higher levels of the anti-inflammatory cytokine IL-10 induced by G18 than AF2122 may play an important role in the more silent infection of G18, which is currently being investigated (K. Jensen and E. J. Glass, unpublished data)." (PMID 29263113, 2018). "As an answer to these questions, the infection of mice deficient for Toll-like receptor 2 (TLR2), TLR4, IL-10, arachidonate 5-lipoxygenase (ALOX5), or arachidonate 15-lipoxygenase (ALOX15) with the M. tuberculosis Δnrp strain showed the same phenotype as WT mice." (PMID 30381350, 2018). "Suppressor activity of IL-10 might help control immune-mediated damage during infection and also limits HIV-specific response favoring viral persistence." (PMID 29342870, 2018). "The excessive production of this cytokine usually results in failure to control the infection, and this could account for why IL-10 was elevated in the MDR-TB participants." (PMID 30583589, 2018). "For non-MDR bacterial infection IL-10 production is required for host survival during infections caused by extracellular and/or highly pro-inflammatory bacteria." (PMID 30279680, 2018). "Thus, MDSCs have the ability to shift the balance of soluble mediators at the site of infection toward suppressive and regulatory cytokines, by releasing high amounts of IL-10 and IL-6." (PMID 30405617, 2018). "However, the levels at day 75 were lower than that at day 30, which was likely caused by the activation of anti-inflammatory response, as evidenced by high levels of IL-10 in vaccinated mice 30 days post-infection." (PMID 30147689, 2018). "Alternatively, their production might have been inhibited by IL-4 and IL-10 which were both increasingly expressed after infection." (PMID 29973271, 2018).
infection (continued). "V2.2-1 infection of IL-10−/− mice resulted in faster control of virus replication during acute infection and reduced initial demyelination; surprisingly however, the severity of demyelination increased 2 weeks after viral control without altering viral persistence." (PMID 30619363, 2018). "High levels of IL-10 have been detected in mice serum after infection with B. microti." (PMID 29304171, 2018). "Although IFN-γ and IL-10 seem to be important cytokines and are induced during infection, other mediators could be more useful as markers of disease progression or in the assessment of the response to treatment." (PMID 30175073, 2018). "During infections, IL-10 production from these Th cell subsets might be an essential mechanism underlying the self-limitation that dampens excessive immune responses and prevents tissue damage." (PMID 29535721, 2018). "Recognition of T. cruzi by the innate and adaptive immune cells trigger the production of cytokines, such as IL-1β, IL-18, IL-6, TNF, and IL-10 during the acute phase of infection which exert profound effects in the killing of parasites and in the modulation of inflammation." (PMID 29774028, 2018). "Diminished levels of IL-10 were also seen at week 10 post-infection." (PMID 30410119, 2018). "The proportion of CD4 T cells secreting TNF-α or IFN-γ and CD8 T cells producing IFN-γ were further elevated in infected IL-10 KO splenocytes (p < 0.001), indicating that expression of IL-10 during naive T cell priming upon infection suppresses the generation of T cell responses." (PMID 30233599, 2018). "During infection, IL-10 inhibits Th1 cells, NK cells and macrophages." (PMID 29304171, 2018). "However, the concentrations of interferon (IFN) γ, tumour necrosis factor (TNF) α, interleukin (IL) 6, and IL-10 were significantly elevated due to infection with T. gondii alone, whilst the levels of IL-1α were down-regulated compared with other groups." (PMID 30186279, 2018). "Importantly, we observed persistent S. Typhimurium infection, mainly in liver and spleen of IL-10−/− and WT mice treated with enrofloxacin after infection." (PMID 29896196, 2018). "Interestingly, with the exception of IL-10, we found comparable cytokine responses between the two strains at 16 weeks post-infection." (PMID 30619289, 2018). "Importantly, our work demonstrated that CAM-treated CD11b+Gr-1+ cells potentiate the production of IL-10, an anti-inflammatory cytokine that plays a central role in infection by limiting the immune response to pathogens and preventing damage to the host." (PMID 29621339, 2018). "Mice of a C57BL/6 background (B6.WT) display a localized, self-healing infection characterized by interferon-γ (IFN-γ) production, while mice of the BALB/c background respond to infection with a preferential production of Th2 cytokines, such as IL-4, IL-10, and IL-13." (PMID 29403488, 2018). "In the present investigation, secretion of IL-10 was present in infected animals, but was more reduced by the F3 than by the NH36 vaccine, as observed by their respective IFN-γ/IL-10 and TNF-α/IL-10 ratios, which characterize a Th1 response against the infection." (PMID 29867949, 2018). "Some results obtained with the high inocula of KR cps- were heterogeneous: the bacterial load 4 days post-infection was spread over 4 logs, IL-10 levels in the lungs were quite variable and some mice showed some bacteria in the digestive tract by bioluminescence." (PMID 29381692, 2018). "However, IL-10 was expressed at low level after 109 Kp52Δwzc infection (53–63 pg/ml), contrasting the higher amount observed after 109 KR cps- infection in some mice." (PMID 29381692, 2018). "Infection increased serum levels of IL-10 at days 7 and 14 p.i.." (PMID 30072754, 2018). "Additionally, IL-10 levels gradually increased in serum with the progression of infection of BALB/c mice with 106 PbA iRBCs, and neutralisation of IL-10 activity leads to symptoms of CM, although not as severe as in infected C57BL/6 mice." (PMID 29367729, 2018).
infection (continued). "However, the levels of IL-6, MCP-1 (CCL2), IL-10, and Arg-1 mRNA were found to be downregulated at 6 weeks post-infection." (PMID 30589840, 2018). "Consistent with this, a previous study reported biphasic activation (an initial peak within 10–30 min and persistent activation from 2 to 8 h after infection) of ERK1/2 in murine macrophages supports positive feedback expression of IL-10 by induced type I IFNs." (PMID 30233599, 2018). "At 24 hours after infection, serum levels of Il-6, IL-17, IL-10, TNFα and IL1β were unchanged and while the levels of Il-6, IL-10, TNFα and IL1β increased in Ddx3xfl/y Vav-iCre relative to control animals at 72h, the difference only reached significance in the case of IL-10." (PMID 30475900, 2018). "Sm-infection was accompanied with increased levels of the regulatory cytokine IL-10." (PMID 30048550, 2018). "The analysis of the data obtained in the present study with immunized and infected dogs indicates that LJM17 antigen induced an outspoken immune response with higher levels of IFN-γ compared to IL-10, which is consistent with expected protective immune mechanisms against infection by L. infantum." (PMID 30519235, 2018). "Thus, increased IL-10 levels during infection of mice with PbA seem to be important for counter-regulating the pro-inflammatory cytokines and ameliorating ECM." (PMID 29367729, 2018). "However, in the validation samples, IL-10 mRNA levels were elevated over the whole 72-h infection period, with maximal expression observed at 6 to 24 hpi." (PMID 29263113, 2018). "Furthermore, in IL-4 absence, significantly higher IL-10 levels were observed in cardiac tissue following infection (Inf WT vs. Inf IL-4−/−, p = 0.004, t = 3.42)." (PMID 30622430, 2018). "WT and IL-10 KO mice were infected with P. chabaudi and monitored during the peak of infection." (PMID 29866139, 2018). "Therefore, IFN-γ and IL-10 are the main hallmarks of infection by L. infantum, and the balance between these cytokines seems to be essential for control of the infection." (PMID 30175073, 2018). "Although we were unable to detect differences between CD4+CD25+ between FIV and CO cats in this study, in comparison to SMM infection indicates that IL-10 expression during acute infection may be more relevant to subsequent viral control than IFN-γ." (PMID 29677149, 2018). "Herein, we hypothesize that in initial phase of infection host cells can downregulate miR-21a-5p expression to reduce IL-10 and increase GBP5 expression thus resulting in improved control of Brucella replication." (PMID 29942317, 2018). "Consistent with the auxin-related genes, the IAA concentration remained at a lower level during the infection in resistant line IL10–1 than that in the control, whereas the IAA concentration was significantly higher in susceptible line CC3 than that in the control, particularly at 2 dpi.." (PMID 30075750, 2018). "We speculated that A54970-mediated inhibition of inflammasome activation might be due to the high levels of IL-10 produced during the in vitro and in vivo infection with this strain." (PMID 30518854, 2018). "Increases in Th2 cytokine (e.g. IL-10) concentration following infection may be a result of immune cells attempting to reduce the potentially damaging effects of the Th1 cytokine-mediated inflammatory reactions without impairing the clearance of Mtb infection." (PMID 30204787, 2018). "During ADE of infection, both the IL-10 as well as IL-6 levels are increased." (PMID 29740424, 2018). "FoxP3+ Tregs secrete IL-10 following primary infection with RSV or IAV." (PMID 29686673, 2018). "The infection with RV tripled the expression of Il10, as seen in all RV-infected groups." (PMID 30406046, 2018). "Thus, EVs from L. amazonensis appear to stimulate the production of IL-6 to attract more phagocytes to the site of infection and to simultaneously induce the production of IL-10 to deactivate the microbicidal effects of recruited cells." (PMID 30627118, 2018).
infection (continued). "Instead, the increase of IL-10 and IL-4 predispose BALB/c mice to infection." (PMID 30697304, 2018). "In addition, epithelial cells and keratinocytes can also secrete IL-10 in response to infection or tissue damage as well as tumor cells." (PMID 29686676, 2018). "Typhimurium will differentially induce IL-10 production during infection." (PMID 30279680, 2018). "Furthermore, fibrillarin knockdown prior to infection led to a reduction of pro-inflammatory cytokines interleukin (IL)-6 and IL-8, and an induction of anti-inflammatory cytokine IL-10 indicative of reduced inflammation." (PMID 30190478, 2018). "However, LMWH-treated IL-10 KO mice were still susceptible to delayed mortality, as two out of four ENO-treated mice (50%) died after day 9 post-infection." (PMID 29866139, 2018). "Moreover, significant elevations in the levels of plasma Th2 cytokines (IL-4, IL-13, and IL-10) and serum enzymes (alanine aminotransferase and aspartate aminotransferase) reflecting altered liver function were detected in response to the infection." (PMID 30619361, 2018). "However, following infection, we observed significantly elevated levels of IL-1β, IL-2, IL-3, IL-5, IL-6, IL-10, IL-17A, MIP-1α, MIP-1β, KC, transforming growth factor β (TGF-β), G-CSF, and GM-CSF in HO-1−/− mice compared to HO-1+/+." (PMID 30428359, 2018). "Our results show that VirB10-induced production of IFN-γ and IL-10 might modulate the balance between immunopathological responses and control of infection." (PMID 30563470, 2018). "After infection with S. aureus for 6 h, the IL-8 and IL-10 peptides were quantitated by ELISA." (PMID 29434603, 2018). "Many reviews of molecular profiling strategies have highlighted the importance of analyzing molecular data in conjunction with other clinical measures of severity (i.e., APACHE, SOFA scores), markers of infection (i.e., procalcitonin), and markers of inflammation (i.e., IL-6, IL-10)." (PMID 30045694, 2018). "Here, the infection induced by Pb18 caused augmented production of IL-10 and IL-6 by the lung tissue of infected animals from the nondiabetic groups." (PMID 30426021, 2018). "We anticipate extending our studies to pedigree lines where a simpler genetic relationship matrix can be established, and to natural infection, over a longer time course, where we can also measure the trajectory of circulating IL-10, pathogen load, shedding, and feed conversion efficiency." (PMID 30463512, 2018). "Increased expression of IL-10 and TNF-ɑ in co-infected cells demonstrates that interaction of both parasites is tightly linked to the host cell types and their various responses to infection." (PMID 30081942, 2018). "Following infection HLA-DR production appears to be maintained and the post-transcriptional effect resulting in reduced cell surface HLA-DR levels was demonstrated to be at least partially dependent on IL-10." (PMID 30212506, 2018). "This delayed increase of Foxp3/decrease of IFN-γ and increase of serum IL-10 level at the late infection stage match previous observations at the late stage of infection of human AE (24, –, 26) and are in agreement with the data usually reported from lymphocyte studies in secondarily infected mice." (PMID 30037796, 2018). "The host’s immune system may have induced secretion of IL-10 in this study as a response to the infection by Acanthamoeba spp." (PMID 30236160, 2018). "Furthermore, production of IL-10 by macrophages is markedly higher in A54970 infection than in A28006 infection." (PMID 30518854, 2018). "The down-regulation of il10 immediately upon infection of NC fish with a subsequent elevation in fins 24 and 48 hpc may reflect that an early inflammation becomes controlled by Il10." (PMID 30204772, 2018).